IL25 (interleukin 25)
Diseases named in the same sentence as IL25 in open-access papers (continued):
Sharing a sentence is not in itself a finding about the gene and the disease.
allergic disease (continued). "TSLP, IL-33, and IL-25 secreted from HNECs were known as “master switches” in the development of allergic diseases." (PMID 34899052, 2021). "Because previous studies have identified TSLP, IL-25 and IL-33 as potent activators of innate lymphoid cells in allergic and non-allergic disease states, we chose to assess potential activation of lung ILC2 by these epithelium-derived cytokines." (PMID 34266437, 2021). "The efficacy of anti-TSLP, anti-IL-33 and anti-IL-25 as monotherapies for treatment of allergic diseases was addressed in a number of studies." (PMID 34084159, 2021). "Among these cytokines, IL-17E (also known as IL-25) is shown to be pro-allergenic, while the role of other Th17 cytokines in allergies is unclear at present." (PMID 32369940, 2020). "IL-17E, called IL-25, is produced by innate immune and respiratory tract epithelial cells and plays an important function in allergy." (PMID 32244562, 2020). "IL-17A, IL-17C, and IL-17F usually trigger host defense response and promote autoimmune inflammatory response, whereas IL-25 (IL-17E) induces Th2 polarization with allergic response." (PMID 32972460, 2020). "IL-25 and IL-33 are epithelial cell-derived cytokines that lead to Th2 cytokine-mediated allergy responses, either directly by the Th2 cell or indirectly via dendritic cell activation." (PMID 32824648, 2020). "For instance in allergic disease, epithelial cells can secrete interleukin 25 (IL-25), IL-33, and thymic stromal lymphopoietin (TSLP), which promote proallergenic responses." (PMID 32582164, 2020). "IL-25 can induce and enhance Th2-type immune responses and plays an important role in some allergic diseases." (PMID 30345318, 2018). "The release of IL-25 has been found to increase when the airway epithelium has been damaged, and this plays an important role in allergic diseases represented by bronchial asthma." (PMID 30345318, 2018). "This shows that innate cytokines, such as TSLP, IL-25, and IL-33, are involved in the development of allergic disease by acting as a link between the innate and adaptive airways." (PMID 28912627, 2017). "The rat anti-mouse IL-25-specific blocking antibody was previously generated in our lab, and widely used by the allergy field." (PMID 27909985, 2017). "IL-17E is also known as IL-25, and because it presents low homology with other molecules of the family and contributes to the induction of allergies, it is thought to have functions different from those of IL-17A." (PMID 28316374, 2017). "Nonetheless, IL-17E (also referred to as IL-25), which shares the lowest homology with IL-17A, was involved in allergy reactions and in immunity against parasites." (PMID 27589729, 2016). "As such, studying how IL‐25 influences human Th2 responses is an important step toward understanding the role of IL‐25‐inducing environmental stimuli in the development of allergic disease." (PMID 26734466, 2015). "In experimental mouse models IL-25 mediates early differentiation towards a Th2 phenotype and development of airway hyper-reactivity and allergic disease." (PMID 24295226, 2013). "The alarmins, IL-25, IL-33, and TSLP activate ILC2s and are linked to allergic diseases." (PMID 41915169, 2026). "Indeed, during allergy and anti-helminth immunity, epithelial cells of damaged barriers release alarmins including IL-25, IL-33, and thymic stromal lymphopoietin (TSLP), but also chemokines such as CXCL1 and CCL11, to promote cell recruitment and inflammation." (PMID 40943268, 2025). "On the one hand, IL-25 is a driver of multiple allergic diseases." (PMID 36119076, 2022). "IL‐25, as a member of the IL‐17 family, mainly contributed to inflammation and allergic disease." (PMID 34128588, 2021).
allergic disease (continued). "Recognizing the significant effect of TSLP, IL-25 and IL-33 on the pathogenesis and development of allergic diseases and the effect of elevated concentrations of these alarmins on the number of allergen components to which the patient was sensitized was analyzed in the ImmunoCap ISAC test." (PMID 34301307, 2021). "IL-17E is also called IL-25 and is related to the type 2 immune response and allergies." (PMID 32070069, 2020). "Furthermore, allergy immunotherapy inhibited the increasing of IL-25 and Th2 cytokines IL-4, IL-5 and IL-13 with induction of CD4+CD25+ Foxp3+ Treg cells." (PMID 29784924, 2018). "The low production of IL-25 may be one of the important factors contributing to the suppression of allergic airway inflammation and airway hyper-responsiveness in allergy immunotherapy." (PMID 29784924, 2018). "Although TSLP, IL-25, and IL-33 have all been shown the contribute to the induction of Th2 responses, there seems to be a division of labour where each of the mediators can have a more prominent role depending on the allergy model under investigation." (PMID 27050744, 2016). "Although there has been substantial evidence to suggest that IL-25 plays critical roles in the regulation of type-2 immune responses against parasitic infections and allergic diseases, its role in tumor progression remains largely unknown." (PMID 26840565, 2016). "Moreover, DCs activated by TSLP enhance allergy-promoting Th2 memory cells by increasing the number of their receptors for IL-25." (PMID 27069818, 2016). "IL-17E (or IL-25) shows the lowest similarity to IL-17A in terms of the amino acid sequence and also promotes Th2 cell-mediated immune responses, thereby contributing to allergic disease and defense against helminthic parasites." (PMID 25152827, 2014). "Thus, IL-33, IL-25 and TSLP are considered to be involved in host defense against nematodes and development of Th2-associated disorders, such as allergy." (PMID 24205109, 2013). "In human subjects however, the involvement of IL-25 and IL-17 in food (peanut) allergy remains unknown." (PMID 24295226, 2013). "The involvement of IL-25 and also IL-17 in food allergic disease remains to be investigated." (PMID 24295226, 2013). "IL-25 can promote the expression of Th2 cytokines and accumulation of eosinophils, inhibit the apoptosis of eosinophils, enhance adhesion between eosinophils and epithelial cells, release cytokines and chemokines by stimulating eosinophils, and thus promote allergy." (PMID 30345318, 2018). "The epithelial cell-derived cytokines IL-25 and IL-33 can potentiate type-2 immune responses by activating both ILC2 and Th2 cells in allergy and helminth infection." (PMID 37337050, 2023). "Studies on humans confirmed the importance of alarmins in IgE-mediated allergies: serum concentrations of TSLP and IL-25 are found to be increased in patients with food allergy, and IL-25 levels appear to correlate positively with atopic severe phenotypes." (PMID 37048784, 2023). "Recent identification of memory Th2 cells with high expression of receptors for IL-25, IL-33, and TSLP supports a role of these cytokines in adaptive immune responses in allergy." (PMID 33945508, 2021). "Innate cytokines including the alarmins IL-25, IL-33, and TSLP are produced by epithelial cells and are key mediators of allergic disease." (PMID 33717078, 2021). "It was found that in patients with an allergy to shrimp, the concentrations of TSLP and IL-25 in the patients’ blood serum were significantly higher than in the control group." (PMID 34301307, 2021). "For example, an allergenic substrate can activate dendritic cells and induce IL-25, TSLP, and allergy-related chemokines." (PMID 30557322, 2018). "In this study thirty children suspected of peanut allergic disease underwent a double-blind placebo controlled food challenge (DBPCFC) and IL-25 and IL-17 plasma levels were determined before and after challenge." (PMID 24295226, 2013).
allergic disease (continued). "As a result of emerging evidence, IL-25, IL-33, and TSLP are important mediators of inflammation during allergic disease and may prove to be key targets for therapeutic intervention." (PMID 35406669, 2022). "Release of TSLP, IL-33, IL-25 and GM-CSF is obviously not restricted to allergy; however, these cytokines mostly contribute to type 2 immune response through specific activation of dendritic cells." (PMID 34084159, 2021). "The role of IL-25, IL-33 and TSLP in various allergic diseases has been studied for several years." (PMID 34301307, 2021). "IL-25 was constitutively expressed in epithelial cells and was released by HDM stimulation and proteases, like trypsin and papain, whereas, it affected the exacerbation of allergic diseases." (PMID 32824648, 2020). "Collectively, our data suggested that deletion of Shp2 impaired IL-25 production in bronchial epithelial cells in vitro, but might yet have minor influence on OVA-induced allergic reaction in vivo." (PMID 28481957, 2017). "(ii) In the allergy propagation phase, re-exposure to ingested food antigens activates emigrated antigen-specific CD4+TH2 memory/effector cells in the small intestine to produce IL-13, resulting in the increase of intestinal IL-25 production." (PMID 27853507, 2016). "IL-33, IL-25 and thymic stromal lymphopoietin (TSLP) are thought to share several roles in immune responses, such as induction of Th2 cytokines by Th2 cells, suggesting that these cytokines contribute to the development of allergic diseases." (PMID 24205109, 2013). "IL-25, IL-33 and TSLP, which are produced by epithelial cells, have a shared biological activity to induce Th2 cytokines, suggesting involvement in the development of allergic diseases." (PMID 24205109, 2013). "Basolateral challenge of the epithelium with HIS induced upregulation of pro-inflammatory cytokines as IL-6 and IL-8; however, other major cytokines involved in the allergic reaction (IL-25, IL-33, and TSLP) were not detectable in the epithelium with or without the addition of HIS." (PMID 38933682, 2024). "Therefore, we suppose that IL-35 may be involved in allergic diseases by regulating the expression of TSLP, IL-33, and IL-25 from HNECs." (PMID 34899052, 2021). "Another explanation is that IL17E, also known as IL25, could propagate production of IL-4 and IL-13 in different organs, which stimulate the expansion of eosinophils, and link between allergic disease and psoriatic disease." (PMID 32468320, 2020). "Furthermore, two important Th2 innate cells, activated eosinophils and basophils, secrete bioactive IL-25, which could up-regulate TSLP, indicating cross-talk between immune cells and structural cells related to allergic disease." (PMID 23437132, 2013).
helminth infection (69 papers, 2012 to 2025). "Supraoptimal ILC2 stimulation by IL-25 resulting from tuft cell Il17rb deficiency or prolonged succinate exposure induces a state of hypoproliferation in ILC2s, also observed in chronic helminth infection." (PMID 40074948, 2025). "In A. suum, the helminth-infection hallmark cytokines IL-13, IL-25 and IL-33 were identified as potential targets of lin-4-5p and let-7-5p, miR-5350d-5p and miR-87a/b-3p, respectively." (PMID 38172997, 2024). "Previous studies showed that Il-25 deficient mice exhibited an increased burden of helminth infection." (PMID 36119076, 2022). "Interleukin-25 and group 2 innate lymphoid cells (ILC2s) defend the host against intestinal helminth infection, and are associated with inappropriate allergic reactions." (PMID 35658010, 2022). "IL-25 is closely linked, in presence and function, with helminth infections, and was first characterized by elevated expression in the small intestine following N. brasiliensis infection, leading to IL-5 production by the then unnamed ILC2s." (PMID 31024526, 2019). "In worm infection models treated with IL-25, BATF deficiency impairs iILC2 cell production." (PMID 39876010, 2025). "IL-17E (also called IL-25) is associated with type 2 T helper cell (Th2) response, promoting Th2-related cytokine production for eosinophil recruitment and contributing to host defense against parasitic helminth infections." (PMID 36620027, 2022). "Secondly, IL-25 also suppresses the inflammation caused by helminth infection." (PMID 36119076, 2022). "In contrast, iILC2 is not present in peripheral tissues in the steady state but can be rapidly elicited at many sites by helminth infection or IL-25 treatment." (PMID 40356895, 2025). "IL-25 specifically promotes the expansion of the iILC2 subset, enhancing resistance to worm infections." (PMID 39876010, 2025). "Some studies suggest that iILC2s are absent from peripheral tissues under steady-state conditions but can be induced at multiple sites by helminth infection or IL-25 administration." (PMID 41041315, 2025). "Numerous reports have underscored the interdependence between tuft cells, IL-25 and ILC2s in facilitating type 2 responses, as observed in helminth infections, or during heightened luminal succinate levels." (PMID 40074948, 2025). "Although iILC2 lacks ST2, it can become ST2+ nILC2-like cells following IL-25 administration or helminth infection, suggesting it can act as progenitors of nILC2-like cells." (PMID 40356895, 2025). "IL-25 is mainly expressed by tuft cells in response to helminth infection to activate ILC2s in the intestine." (PMID 39085648, 2024). "Gastrointestinal DCLK1+ tuft cells constitutively express IL-25, and its expression is further increased after helminth infection, leading to IL-13 secretion by ILC2s." (PMID 38061015, 2024). "Gastrointestinal DCLK1+ tuft cells constitutively express IL-25, and its expression is further increased after helminth infection, leading to IL-13 secretion by type 2 innate lymphoid cells (ILC2s)." (PMID 38061015, 2024). "IL-25 assumes a significant role in coordinating the intestinal response to helminth infections, a fact underscored by its multifaceted impact on various influencing factors." (PMID 38203591, 2023). "IL-25-activated ILC2 cells help protect the host against helminth infection while exacerbating allergic-like inflammation and tissue damage in the lung." (PMID 37781372, 2023). "In contrast, the downregulation of IL1B observed on day 3 probably results in IL-25 and IL-33 suppression, supporting chronic helminthic infection." (PMID 37600806, 2023).
helminth infection (continued). "On the other hand, iILC2s express high levels of KLRG1 (a C-type lectin receptor) and IL-17RB (an IL-25 receptor component), and expand and transiently appear after helminth infection and recombinant IL-25 administration." (PMID 37163450, 2023). "Particularly in mice, tuft-cell-derived IL25 further activates the tissue-resident group 2 innate lymphoid cells (ILC2) at the resting lamina propria in the small intestine after helminth infection." (PMID 37893107, 2023). "Altogether, our data suggest that intestinal adiponectin expression induced by helminth infection through the regulation of IL-25 promotes worm clearance and intestinal barrier function." (PMID 37635188, 2023). "During helminth infection, IL-25 derived from tuft cells induces IL-13 secretion from ILC2s, which leads to epithelial remodeling by increasing the number of tuft and goblet cells." (PMID 36941691, 2023). "Following helminth infection, tuft cells undergo rapid IL4Rα-dependent amplification directed by Pou2f3 and secrete IL25." (PMID 37893107, 2023). "The critical functional role of tuft cells was not appreciated until two studies in 2016 demonstrated that they sense and respond to intestinal helminth infection through the release of IL-25 which primes protective type 2 immune responses in the gut." (PMID 37887321, 2023). "During acute helminth infection, tuft cells produce IL-25 and promote their own hyperplasia via a positive feedback loop, which is critical for helminth clearance." (PMID 37163450, 2023). "Natural ILC2s (nILC2) are IL-33 responsive and can be found in the lungs in homeostatic conditions, whereas inflammatory ILC2s (iILC2) respond to IL-25 and emerge after IL-25 treatment or during helminth infection." (PMID 36969171, 2023). "Upon helminth infection, various types of alarmin cytokines, including IL-25, IL-33, and thymic stromal lymphopoietin (TSLP) were secreted from intestinal epithelial cells." (PMID 37635188, 2023). "IFN-γ has been previously reported to be suppressed by IL-25 during helminth infection, however, we are the first to show IL-25 regulates epithelial-derived virus-induced IFNs during allergic inflammation." (PMID 35508632, 2022). "Immunologically, chronic helminth infections are characterized by a skewing towards Th2 response, in which IL-25 plays a critical role." (PMID 36119076, 2022). "Although ILC2s are normally tissue resident cells, they can migrate from one tissue to another in response to exogenous IL-25 and helminth infection." (PMID 35784368, 2022). "Of note, ChAT+ ILC2s are strongly induced by type 2 inflammatory conditions, such as helminth infection, Alternaria sensitization, and IL-25 and IL-33 treatment." (PMID 35707544, 2022). "Similar to the helminth infection, IL-25 recruits ILC2, which mediates the clearance of protozoan parasites." (PMID 36119076, 2022). "In small intestine, tuft cells become the essential source of cysteinyl leukotriene and activate ILC2s in cooperation with IL-25 following helminth infection." (PMID 35707544, 2022). "Group 2 ILCs (ILC2s) were first reported as cells that produce type 2 cytokines, such as IL-5 and IL-13, in response to IL-33 and IL-25 in the adipose tissue and small intestine during helminth infection." (PMID 35757747, 2022). "As one of the main sources of IL-25 in human intestinal, tuft cells are rapidly increased during helminth infection." (PMID 36119076, 2022). "Tissue-specific ILC2 phenotypes become pertinent in murine pulmonary helminth infections, when Klrg1high inflammatory ILC2s (iILC2s) expand in response to IL-25, then transmigrate from the gut to the lung to clear infection." (PMID 36044863, 2022). "Tuft cells are the primary producers of IL-25 in the small intestine, undergo hyperplasia in response to IL-13 during helminth infection, and can be identified by their unique expression of DCLK117,20–22." (PMID 35534698, 2022).